CDX1 (caudal type homeobox 1)
Diseases named in the same sentence as CDX1 in open-access papers (continued):
Sharing a sentence is not in itself a finding about the gene and the disease.
colorectal tumors (3 papers, 2014 to 2022). "Conversely, compound deletion of Ehf and Cdx1 in mice reduced expression of colonic differentiation markers and significantly accelerated colorectal tumour progression." (PMID 35606410, 2022). "Notably, in this regard, a number of studies report that CDX family members are involved in regulating tight junctions in intestinal epithelium and colorectal tumors, suggesting a functional conservation of CDX1 in EMT from various tissues." (PMID 25068460, 2014).
mesenchymal chondrosarcoma (3 papers, 2014 to 2023). A morphologic variant of chondrosarcoma arising from bone and soft tissue. "Recently, a novel fusion between IRF2BP2 and the CDX1 homeobox gene was described in a patient suffering from a mesenchymal chondrosarcoma." (PMID 24970810, 2014). "More recently, recurrent hairy/enhancer-of-split related with YRPW motif 1—nuclear receptor coactivator 2 (HEY1-NCOA2) and interferon regulatory factor 2 binding protein 2 gene—caudal type homeobox 1 (IRF2BP2-CDX1) fusions have been identified in mesenchymal chondrosarcomas." (PMID 36674874, 2023).
ovarian carcinoma (3 papers, 2019 to 2022). A malignant neoplasm originating from the surface ovarian epithelium. "The lncRNA ATB binds to EZH2 and downregulates the expression of DAB2IP, CDH1, LATS2, FOXC1 and CDX1, thus facilitating the progression of ovarian cancer." (PMID 34890108, 2022). "Although the anti‐tumour roles of CDX1 and FOXC1 have been reported, more evidence about their function in repressing ovarian cancer should be provided in future." (PMID 33336896, 2021). "Therefore, we considered CDX1 and FOXC1 are targets of EZH2 in ovarian cancer." (PMID 33336896, 2021).
adenoma (2 papers, 2015 to 2025). A neoplasm arising from the epithelium. "In trans-Apc+/−Cdx1+/− mice, adenoma cells possessed only the mutant Apc allele and the wild-type (wt) Cdx1 allele, which rendered genetic analysis of the role of Cdx1 in Apc+/− mice challenging." (PMID 40399276, 2025). "To delete Cdx1 in adenomas in Apc+/− mice, we subsequently generated cis-Apc+/−Cdx1+/− mice that carried both Apc and Cdx1 deletion mutations on the same Chr 18 homolog via meiotic recombination." (PMID 40399276, 2025).
anorectal malformation (2 papers, 2021 to 2022). "Variants in the HOXL gene CDX1 are associated with anorectal malformations." (PMID 34671974, 2022). "A causative role is further substantiated by the relationship between CDX2 and other proteins encoded by genes that were previously linked to caudal abnormalities in humans, for example, TBXT (sacral agenesis and other vertebral segmentation defects) and CDX1 (anorectal malformations)." (PMID 34671974, 2022). "For instance, CREB3L3 and CDX1 are not assigned any disorders on OMIM but are on the ‘severe hypertriglyceridaemia’ panel and ‘nonsyndromic familial congenital anorectal malformations’ panel, respectively, in the Genomics England PanelApp." (PMID 33836063, 2021).
colorectal adenoma (2 papers, 2015 to 2020). An adenoma that arises from the colon or rectum. "A single case of colorectal adenoma was observed in villin-cre/Dkk3 mice after chemical induction, showing a higher level of expression of CDX1, ki-67, and c-erB2 than that observed in normal mucosa." (PMID 33425757, 2020).
dysplasia (2 papers, 2020 to 2024). A usually neoplastic transformation of the cell, associated with altered architectural tissue patterns. "CDX1/CDX2 genes seem to have a key role in intestinal dysplasia reprogramming." (PMID 38542354, 2024).
gastric adenocarcinoma (2 papers, 2022 to 2023). "In gastric adenocarcinoma, increased promoter methylation of transcription factors CDX1/2 and KLF5, which are the downstream targets of the sonic hedgehog (SHH) signaling, caused reduced expression of CDX1 and KLF5 and elevated expression of CDX2." (PMID 36810098, 2023). "In gastric adenocarcinoma, significant DNA methylation of Shh transcription factors CDX1/2 and KLF5 correlated with decreased expression of CDX1 and KLF5 and an increased expression of CDX2." (PMID 35563709, 2022).
myoepithelial tumor (2 papers, 2025). A benign or malignant tumor characterized by the presence of cells that show myoepithelial differentiation. "It is uncertain at this point in time if the presence of an IRF2BP2 and CDX1 gene fusion contributes to or affects the vascular milieu of myoepithelial tumors of soft tissue." (PMID 40978976, 2025). "Given its rarity, the prognostic significance of the IRF2BP2::CDX1 gene fusion in myoepithelial tumors of soft tissue is uncertain, with surgical excision being the mainstay of treatment in morphologically low-grade tumors at this point in time." (PMID 40978976, 2025). "Our case technically would be the third myoepithelial tumor of soft tissue to harbor an IRF2BP2 gene fusion and the first fully characterized case with a novel CDX1 gene fusion partner and rare morphologic features." (PMID 40978976, 2025).
allergic rhinitis (1 paper, 2017). Inflammation of the nasal mucous membranes caused by an IgE-mediated response to external allergens. "We were able to identify one gene with significant cis-mQTL for allergic rhinitis, caudal-type homeobox 1 (CDX1)." (PMID 28149331, 2017).
asthma (1 paper, 2017). "Moreover, most SNPs identified were not located closest to the gene they were linked to through cis-mQTLs counting the one linked to CDX1 located in a gene previously associated with asthma and atopic dermatitis." (PMID 28149331, 2017).
colon adenocarcinoma (1 paper, 2021). "In contrast, colon adenocarcinoma showed a significant enrichment of TFs such as CDX2 (26.5%), CDX1 (24%), HOXA13 (22%), HNF4G (37.2%), and TCF4 (36%) in gained peaks; and FOS::JUNB (45.4%), FOS::JUND (47.5%) and JUNB (46.3%) in lost peaks." (PMID 34090364, 2021).
colorectal adenocarcinoma (1 paper, 2022). The most common type of colorectal carcinoma. "In addition, we found that three (CDX1, CDX2, and KLF4) of the four transcription genes (CDX2, KLF4, CDX1, and ELF3) with low expression in CSCC also showed low expression in colorectal adenocarcinoma, while ELF3 achieved the opposite result in colorectal adenocarcinoma." (PMID 35194959, 2022).
enterocolitis (1 paper, 2012). An inflammatory process affecting the small intestine and colon. "Whereas, the reduced expression of cdx-1 and cdx-2 genes were associated with the development of enterocolitis in intestinal mucosa." (PMID 22824143, 2012).
intestinal cancer (1 paper, 2012). "In adults, CDX1 expression is restricted to intestinal epithelium and aberrant expression has been linked to intestinal cancer." (PMID 23185413, 2012).
intestinal tumors (1 paper, 2025). "Here, we show that complete loss of Cdx1 or concurrent loss of Cdx1/2 increased the stemness and malignancy of intestinal tumors." (PMID 40399276, 2025). "The loss of Cdx1 did not affect the number or size of intestinal tumors in Apc+/− mice." (PMID 40399276, 2025).
leukaemias (1 paper, 2012). "In particular, CDX1 is an upstream regulator of Hox-gene expression that has been implicated in malignancies such as leukaemias." (PMID 23185413, 2012).
mesenchymal neoplasms (1 paper, 2025). "We identified three tumors in our epigenetically distinct METs group that carried fusions described in molecularly defined, non-MET tumor types, i.e., EWSR1::NFATC2-rearranged mesenchymal neoplasms and IRF2BP2::CDX1-rearranged neoplasm." (PMID 39636306, 2025).
metastatic colorectal cancer (1 paper, 2025). "In metastatic colorectal cancer, this heterogeneity can be detected through the distinct expression patterns of caudal type homeobox 1 (CDX1), CDX2, and/or catenin beta 1 (CTNNB1)." (PMID 40565003, 2025).
sirenomelia (1 paper, 2025). Sirenomelia is a rare, genetic, developmental defect during embryogenesis disorder characterized by fusion of the lower limbs and associated with some degree of lower extremity reduction and persistent vitelline artery. "Contemporary molecular investigations have implicated several developmental genes in sirenomelia pathogenesis, including HLXB9, CDX1, and various members of the HOX gene family." (PMID 41556023, 2025).
tumor (40 papers, 2012 to 2025). "CDX1 is a transcription factor regulating the normal development and differentiation of the intestinal epithelium and is associated with tumor suppressing potential in the colon." (PMID 37509233, 2023). "CDX1 (together with CDX2) can function as a tumor suppressor and concomitant loss of CDX1 can significantly increase the incidence of tumors APC(Min/ +)-Cdx2 mice." (PMID 35715570, 2022). "Cdx1 and Cdx2, two of the three mammalian orthologues of pal-1/caudal, have been implicated in the formation of epithelial-derived tumours." (PMID 31923384, 2020). "Together, these observations indicate a potential role of CDX1 loss in tumor development." (PMID 30909444, 2019). "CDX1, a known driver of intestine-specific gene expression and a tumor suppressor, is frequently silenced by promotor methylation in CRC." (PMID 39472498, 2025). "Cdx1 and Cdx2 mRNA were detectable in the colonic tumor organoids derived from Apc+/− mice but were expressed at significantly lower levels than those observed in normal colonic epithelium." (PMID 40399276, 2025). "Three additional TFs (SMARCA1, DUX4, and CDX1) were identified as potential direct or indirect targets of the HPV genome and were significantly associated with tumor progression in mammalian systems." (PMID 41012596, 2025). "Histologically, both tumors with IRF2BP2::CDX1 rearrangement (cases 8–9) showed a well-circumscribed lesion composed of bland epithelioid tumor cells in a chondromyxoid stroma." (PMID 39636306, 2025). "Four of the top 5 regulons in stromal or tumor region were overlapped, including CDX1, IRF8, HNF4A, and CREB3lL1." (PMID 38729966, 2024). "By contrast, inactivation of EHF and CDX1 in well-differentiated CRC cells triggered tumour de-differentiation." (PMID 35606410, 2022). "circPPFIA1s upregulated tumor-suppressing CDX1 expression and conversely downregulated oncogenic RAB36 by decoying miR-155-5p and by sequestering HuR, respectively." (PMID 36224588, 2022). "CDX1 encodes a key regulator of differentiation of enterocytes and its expression is decreased or lost in CRC cell lines and CRC tumor tissue." (PMID 35715570, 2022). "circPPFIA1s upregulate tumor-suppressing CDX1 by decoying CDX1-targeting miR-155-5p and downregulate oncogenic RAB36 by sequestering HuR." (PMID 36224588, 2022). "CDX1, a tumor-suppressor, was selected by RT-qPCR validation and reference search for further studies." (PMID 36224588, 2022). "While re-expression of EHF alone failed to re-induce differentiation of these tumours, combined re-expression of EHF and CDX1 re-induced expression of multiple enterocytic differentiation markers and gland formation, and inhibited tumour growth and metastasis." (PMID 35606410, 2022). "Previous reports showed that EZH2 targets a cascade of tumour suppressors, such as CDX1, FOXC1, LATS2, CDH1 and DAB2IP." (PMID 33336896, 2021). "MLH1, APC, PTEN, P16, and CDX1/2 are bona fide TSGs whose promoter hypermethylation and tumor-suppressing functions in CRC have been experimentally verified." (PMID 32678024, 2020). "Its tumor promoting function mainly consists of promoting cell proliferation, metastasis and chemoresistance by suppressing Caudal-Type Homeobox 1 Protein (CDX1) and MAPK13 and MAPK14, respectively." (PMID 31450858, 2019). "The gene CDX1 has also been predicted to contribute to distinguishing different PDX tumor tissues at the expression level." (PMID 31456818, 2019). "Here, we found that CDX1 was significantly higher in tumour compared to that in normal tissues by analysing the CHOL data obtained from TCGA database." (PMID 31523056, 2019). "For example, the CDX1 gene, with hypermethylation detected in both tumor and adjacent tissues, had 31 CG dinucleotides in a 326 bp fragment, which was 53–94% methylated in most samples." (PMID 28418032, 2017).
tumor (continued). "Sequencing analysis of the PCR products confirmed the presence of both isoforms fused to exon 2 of CDX1, i.e., an IRF2BP2-CDX1 fusion transcript was confirmed in the tumour RNA." (PMID 23185413, 2012). "Specific genes downregulated in HG tumours which showed significantly higher promoter methylation included the developmental transcription factors CDX1, CDX2, GATA6, HNF1A, the marker of colonic differentiation, DPP4, and the markers of LGR5+ intestinal stem cells, ASCL2, LGR5." (PMID 40473896, 2025). "Loss of CDX1 expression may contribute to epithelial identity erosion and activation of EMT programs, central to metastasis and tumor progression." (PMID 41012596, 2025). "Among the 17 overexpressed genes, CDX1 (caudal type homeobox 1) had the highest fold difference in tumor versus non-tumor tissues followed by SI (sucrase-isomaltase, aka alpha-glucosidase), KRT16 (keratin 16) and SERPINB5 (serpin peptidase inhibitor, clade B (ovalbumin), member 5)." (PMID 28418924, 2017). "Taken together, these data indicate that EHF and CDX1 are critical regulators of CRC differentiation and suppressors of tumour progression." (PMID 35606410, 2022). "CDX-1, an intestine-specific gene, is generally downregulated in CRC and acts as a tumor-suppressor by hindering the transcriptional activity of β-catenin/T-cell factor." (PMID 36224588, 2022). "Further elucidation of the signalling and transcriptional events which regulate EHF and CDX1 expression may therefore further unveil the hierarchy of differentiation loss in CRC, and uncover potential therapeutic strategies for CRC based on the re-induction of EHF/CDX1-driven tumour differentiation." (PMID 35606410, 2022). "As tumor suppressors, circPPFIA1-L and -S negatively control the metastatic potential of CRC via two pathways: as a sponge of miR-155-5p, upregulating CDX1 expression; and as a sponge of HuR, downregulating RAB36 expression." (PMID 36224588, 2022). "Of note, although CDX1 and CDX2 were found to be both inactivated and underexpressed, several TFs such as KLF5 or ATOH1 with established tumor suppressor roles in colorectal cancer were only found inactivated via SCIRA." (PMID 33083012, 2020). "In the case of colon, our results in the scRNA-Seq data confirm a tumor suppressor role for TFs such as CDX1/CDX277, but also serve to reinforce a novel putative tumor suppressor role for ATOH178, for the autophagy inducer TRIM3162 and KLF579." (PMID 33083012, 2020). "Dedifferentiation markers, CK20 and CDX1, and inflammatory cytokine IL6 were also elevated in these tumours as was the EMT transcription factor Snail." (PMID 28300841, 2017). "The presence of the IRF2BP2-CDX1 fusion gene was tested for in specimens from tumour 2–4 using primer combinations IRF2BP2-926F and CDX1-771R." (PMID 23185413, 2012). "Histological examination revealed that HCT116EHF + CDX1 tumours were more differentiated, evidenced by increased gland formation and expression of the differentiation markers VIL1 and KRT20, compared to HCT116EV, HCT116EHF or HCT116CDX1 tumours." (PMID 35606410, 2022). "Interestingly, using VIPER-D, there was only moderate correlation with SCIRA’s predictions, with VIPER-D not predicting preferential inactivation and failing to predict inactivity of established tumor suppressors such as KLF5 and CDX1." (PMID 33083012, 2020). "Sodium bisulfite sequencing (BSP) was used to validate the 6 randomly selected candidate islands, in which the results of 5 mapped genes (ANKRD45, CDX1, APC, HOXD3 and TUBB6) showed significant differences in the 10 pairs of validation tumor and adjacent tissue cohorts." (PMID 28418032, 2017). "Moreover, FOXA1, FOXA2, and FOXA3 were also grouped together with the tumor/invasion suppressor genes EPHB2 and EPHB3, and with the intestine-specific differentiation genes CDX1 and CDX2 (cluster 2)." (PMID 29155818, 2017).
tumor (continued). "Of note, it seems to be a fusion driven tumor, with Hes Related Family BHLH Transcription Factor With YRPW Motif 1: nuclear receptor coactivator 2 (HEY1-NCOA2) and interferon regulatory factor 2 binding protein 2: caudal type homeobox 1 (IRF2BP2-CDX1) fusions having recently been described." (PMID 36158667, 2022). "In the same manner as the CDX2 investigation, we set a cutoff point of 50% tumor cells to assess whether a tumor is positive or negative for CDX1 protein expression." (PMID 29682204, 2018). "Among the 17 upregulated genes, we selected the top five, i.e. CDX1, SI, KRT16, HOXA10, and SERPINB5 for validation using RT-PCR in the 20 pairs of tumor and non-tumor tissues that were not used in RNA-seq." (PMID 28418924, 2017).